LGR5 (leucine rich repeat containing G protein-coupled receptor 5)
Diseases named in the same sentence as LGR5 in open-access papers (continued):
Sharing a sentence is not in itself a finding about the gene and the disease.
endometrioid adenocarcinoma (3 papers, 2021 to 2024). An adenocarcinoma characterized by the presence of malignant glandular epithelial cells resembling endometrial cells. "SOX9+LGR5+ is the dominant signature in serous endometrial and some endometrioid adenocarcinomas and is positively associated with the ‘Copy-Number high’ molecular subtype from TCGA, as well as the clinically more aggressive stage III and IV adenocarcinomas." (PMID 34857954, 2021). "SOX9+LGR5+ was the dominant signature in serous endometrial (63%) and some endometrioid adenocarcinomas (24%) and was positively associated with the ‘Copy-Number high’ molecular subtype from TCGA, as well as the clinically more aggressive stage III and IV adenocarcinomas." (PMID 39229264, 2024). "Unlike LGSC, high grade serous carcinoma (HGSC), clear cell carcinoma, endometrioid carcinomas displayed various epithelial-stromal LGR5 expression." (PMID 35778589, 2022). "The first, characterized by SOX9+LGR5+, occurs in 63% of serous and 24% of endometrioid adenocarcinomas." (PMID 34857954, 2021). "Indeed, all the copy-number-high tumors considered in our analysis (31 serous and 7 serous-like endometrioid adenocarcinomas) were classified as SOX9+LGR5+." (PMID 34857954, 2021).
esophageal squamous cell carcinoma (3 papers, 2011 to 2025). Esophageal squamous cell carcinoma (ESCC) is a type of esophageal carcinoma (EC) that can affect any part of the esophagus, but is usually located in the upper or middle third. "We investigated Lgr5 expression in four esophageal squamous cell carcinoma cell lines (KYSE70, Eca9706, Eca109, and KYSE450) by western blot and qRT-PCR, respectively." (PMID 28404917, 2017). "High LGR5 expression enhanced tumor invasion in cervical, rectal, CRC, lung, ESCC (oesophageal squamous cell carcinoma), thyroid, and hepatic cancers." (PMID 39821694, 2025). "No LgR5 expression was found in specimen with esophageal SCC." (PMID 21345220, 2011).
gastritis (3 papers, 2012 to 2024). Inflammation of the stomach. "A variety of additional studies have since confirmed an expansion of the Lgr5+ stem cell pool in human H. pylori–positive gastritis or intestinal metaplasia, relative to H. pylori–negative normal gastric mucosa in geographically diverse patient cohorts." (PMID 39191487, 2024).
head and neck squamous cell carcinoma (3 papers, 2021 to 2024). A squamous cell carcinoma that arises from any of the following anatomic sites: lip and oral cavity, nasal cavity, paranasal sinuses, pharynx, larynx, and salivary glands. "The therapeutic approach of using LGR5 even as a biological target was recently very successful in patients with recurrent or metastatic head and neck squamous cell carcinoma (HNSCC) as a phase 2 study (NCT03526835)." (PMID 39769183, 2024).
hyperplastic polyp (3 papers, 2015 to 2021). A polyp found mainly in the stomach and colon. "To determine if the organization of the stem cell niche was disrupted in benign lesions, we examined the expression of LGR5 in hyperplastic polyps (HPPs, n = 7)." (PMID 25728748, 2015). "In hyperplastic polyps (group 1), there was a significant decrease in the expression of PROM1 (p: 0.01), POU5F1 (p: 0.02), LGR5 (p: 0.01) and REX1 (p: 0.01) genes compared to the control group." (PMID 34452555, 2021).
intrahepatic cholangiocarcinoma (3 papers, 2017 to 2025). A carcinoma that arises from the intrahepatic bile duct epithelium in any site of the intrahepatic biliary tree. "It has been reported that LGR5 and EMT-related transcription factors are co-expressed in intrahepatic cholangiocarcinoma, but re-verification of their LGR5 expression data by immunohistochemistry and re-verification RNA in situ is desired." (PMID 35123536, 2022).
liver diseases (3 papers, 2021 to 2024). "Ethanol-induced liver disease damages ISCs through dysregulation of the ß-catenin signaling, a regulator of leucine-rich repeat-containing G-protein coupled receptor 5 (Lgr5) and other ISC markers in the small intestine of mice." (PMID 33390852, 2021). "The PTEN-mediated AKT/β-catenin signaling pathway enhances the proliferation and expansion of Lgr5+ hepatocytes, plays an important role in various liver diseases, such as alcoholic liver damage and pharmacological liver injury, and can cause tumors when disordered." (PMID 39684555, 2024). "Our research also illustrates FXR and PPARα may be potential drug targets for liver diseases since they can regulate Lgr5+ cells fate." (PMID 36168631, 2022).
malignant glioma (3 papers, 2014 to 2015). A grade III or grade IV glioma arising from the central nervous system. "Therefore, LGR5 may be a valuable biomarker for the molecular diagnosis and a novel target for gene therapy of malignant gliomas." (PMID 24172981, 2014).
melanoma (3 papers, 2016 to 2022). A malignant, usually aggressive tumor composed of atypical, neoplastic melanocytes. "In addition, the increased expression of LGR5 in the bad responders and its correlation with outcome could mark a higher de-differentiation, where the melanoma tumors express markers of neuroectodermal origin." (PMID 36012390, 2022). "By analyzing clinical samples from melanoma patients with different grades of stemness, we noted that HDGF and LGR5 correlated with the expression of a commonly used CSC marker, CD133, which was co-localized in the microvascular regions of melanoma tissues." (PMID 34106558, 2021).
metastatic colorectal cancer (3 papers, 2023 to 2025). "Interestingly, a recent study showed LGR5-negative cells can drive metastatic colorectal cancer." (PMID 38609520, 2024).
neuroendocrine tumors (3 papers, 2013 to 2020). "Although LGR5 function in endocrine cells and neuroendocrine tumor cells remains unclear, LGR5 might represent a putative stem cell marker of matured neuroendocrine cells and neuroendocrine tumor of the pancreas." (PMID 24133453, 2013).
pancreatic adenocarcinoma (3 papers, 2013 to 2019). "Prospective isolation and molecular and biological characterisation of subpopulations of putative progenitor cells in pancreatic adenocarcinomas will be required to obtain a better understanding of the relationship between progenitor populations marked by GCTM-5, SOX9, LGR5, and DCLK1." (PMID 30814526, 2019). "LGR5 and BMI1 are stem-cell markers coexpressed with DCLK1 in the intestine, regulated downstream of DCLK1 following radiation injury in intestinal epithelial DCLK1 knockout mice, and markers of populations of cells with tumor stem cell activity in intestinal adenomas and pancreatic adenocarcinoma." (PMID 24885928, 2014).
pancreatic ductal adenocarcinoma (3 papers, 2013 to 2022). An infiltrating adenocarcinoma that arises from the epithelial cells of the pancreas. "Our findings suggested that decreased LGR5 expression in the fat invasion front is associated with more aggressive biological behavior in pancreatic ductal adenocarcinoma, with higher tumor grade, EMT phenotype, and higher vascular invasion." (PMID 35123536, 2022). "Although some reports have indicated that high LGR5 expression is associated with a poor prognosis, others have used RNAscope, which is considered to be more reliable, and have reported that high LGR5 expression correlates with a good prognosis specifically in pancreatic ductal adenocarcinoma." (PMID 33676447, 2021). "LGR5 expression was analyzed in 40 pancreatic ductal adenocarcinoma cases with RNAscope, which is a newly developed high-sensitivity in situ hybridization method." (PMID 35123536, 2022).
rectal cancer (3 papers, 2016 to 2021). A primary or metastatic malignant neoplasm that affects the rectum. "The study aimed to delineate the gene expression profile of LGR5, HES1 and ATOH1 in young Egyptian rectal cancer (RC) patients and investigate the correlation between expression profiles and clinical outcome." (PMID 34582650, 2021). "Analysis of the rectal cancer dataset showed upregulation of stemness markers, NANOG and LGR5." (PMID 28689994, 2017).
Sepsis (3 papers, 2022 to 2025). Sepsis is defined as life-threatening organ dysfunction caused by a dysregulated host response to infection. "In a murine model of sepsis-induced intestinal barrier injury, induction of Lgr5+ expression in the colon accelerated epithelial cell proliferation while suppressing apoptosis, thereby preserving colonic morphology under TNF-α–induced damage." (PMID 41316490, 2025). "‌ Previous study in a murine sepsis model has shown that induction of Lgr5+ expression within the intestine supports the preservation of colonic architecture, highlighting the role of intestinal Lgr5+ cells in maintaining epithelial integrity under inflammation." (PMID 41316490, 2025).
small intestinal adenomas (3 papers, 2015 to 2025). "This was confirmed by in situ hybridization with a probe detecting the mRNA expression of Lgr5 or Smoc2 in small intestinal adenomas of ApcMin mice." (PMID 30177706, 2018).
thyroid tumor (3 papers, 2015 to 2018). A benign or malignant neoplasm affecting the thyroid gland. "We tested the hypothesis that overexpression of the CSC marker, LGR5, is associated with markers of thyroid tumor aggressiveness, including cellular migration, features of histological aggressiveness, loco-regional metastases, and presence of the BRAFV600E mutation." (PMID 26416247, 2015). "In addition to cellular models of PTC, frozen human thyroid tumors expressed significantly more LGR5 by mRNA and protein analysis than adjacent benign frozen thyroid tissue samples (n = 4 normal tissue samples, n = 6 tumor samples)." (PMID 26416247, 2015). "Stem-cell markers, such as Lgr5 (also a Wnt target gene), may be useful for locating thyroid cancer stem cells in order to verify their presence and disclose their organization within thyroid tumors." (PMID 29642644, 2018).
virus infection (3 papers, 2020 to 2025). "In summary, our findings highlight a link between intestinal crypt cells response and virus infection that regulates Paneth cells function and Lgr5 ISCs fate." (PMID 31959773, 2020).
arthrosis (2 papers, 2022 to 2024). "Potential novel associations included COLGALT2 and arthrosis (rs35937944, p.Tyr212Cys, P = 2 × 10−14), LGR5 and carcinoid syndrome (rs200138614, p.Cys712Phe, P = 4 × 10−9), and GREB1 and female infertility (rs755857714, p.Arg1339His, P = 4 × 10−9)." (PMID 39563277, 2024). "In addition, enhanced expression of LGR5 and RSPO2 was detected in chondrocytic differentiation of human chondrocytes in advanced stage of osteoarthritis, while elevated expression of LGR6 and RSPO1 was observed in osteogenic differentiation of SaOS‐2 cells." (PMID 35668632, 2022).
breast tumor (2 papers, 2020 to 2021). "Using RNA in situ hybridization, we thoroughly investigated LGR5 expression in normal, benign, and malignant human breast tumors." (PMID 34493772, 2021).
ductal carcinoma in situ (2 papers, 2020 to 2021). "We investigated the clinical importance of LGR5 in BC and ductal carcinoma in situ (DCIS) to explore LGR5 as a biomarker and a therapeutic target." (PMID 32522170, 2020). "LGR5 expression has not been observed in normal lactiferous ducts and terminal duct lobular units, whereas LGR5-positive cells have been specifically observed in the basal myoepithelium of ducts in the regenerative tissues, ductal carcinoma in situ, and in ducts surrounded by invasive cancer cells." (PMID 34493772, 2021).
Endometrial adenocarcinomas (2 papers, 2021 to 2024). "Endometrial adenocarcinomas displayed two main signatures that were characteristic of the proliferative phase endometrium, SOX9+LGR5+ and SOX9+LGR5−, indicating differences in pathogenesis and disease progression." (PMID 39229264, 2024). "Endometrial adenocarcinomas have two main signatures, SOX9+LGR5+ and SOX9+LGR5−, indicating that these distinct transcriptomic signatures reflect differences in pathogenesis and disease progression." (PMID 34857954, 2021). "The more advanced stages of endometrial adenocarcinomas (stages III and IV) have a greater SOX9+LGR5+ signal (Wilcoxon test, stages I + II against stages III + IV, P value 7.54 × 10−6)." (PMID 34857954, 2021).
epithelial dysplasia (2 papers, 2011 to 2023). "Chronic activation of LgR5 expressed by BE in these putative pluripotent cancer-initiating cells may sustain inflammation responses, mediate resistance to apoptosis and promote further progression of the metaplasia - intraepithelial neoplasia - carcinoma sequence." (PMID 21345220, 2011).
gastric adenoma (2 papers, 2013 to 2017). A neoplastic polyp that arises from the stomach. "Lineage tracing has confirmed cells with LGR5 expression to be the initiating cells of gastric adenomas in animal models." (PMID 28968998, 2017). "Most gastric adenomas (GAs) contain a number of LGR5-expressing tumor cells that typically reside at the basal areas of tumor glands in a similar manner to Lgr5+ cells in the intestinal mucosa, as well as in IMs." (PMID 24340024, 2013).
gastrointestinal carcinoma (2 papers, 2012 to 2013). "To investigate its expression in non-neoplastic and neoplastic human tissue, we evaluated the transcriptional expression of LGR5 in human clinical specimens composed of a broad range of hepato-gastrointestinal carcinomas." (PMID 22530031, 2012).
medulloblastoma (2 papers, 2013). A malignant, invasive embryonal neoplasm arising from the cerebellum. "Our key findings, specifically the over-expression of LGR5 and GPR64 in the WNT subgroup tumors and F2R and FZD2 in all medulloblastoma, were mirrored in three independent international cohorts of subgrouped medulloblastoma." (PMID 24252460, 2013).
prostate carcinoma (2 papers, 2019 to 2020). A carcinoma that arises from epithelial cells of the prostate gland. "We have previously shown that LGR5 is present in prostate cancer." (PMID 32256979, 2020).
sarcopenia (2 papers, 2024 to 2025). Progressive decline in muscle mass due to aging which results in decreased functional capacity of muscles. "Among them, MYH8, HOXB2, C1QA, CDKN1A, and SLC38A1 are associated with sarcopenia, and in this study, LGR5, SERPINA5, and TPPP3 genes were found to be associated with Sarcopenia for the first time." (PMID 38229116, 2024). "In patients with sarcopenia, the expression of TPPP3, C1QA, LGR5, MYH8, and CDKN1A genes are upregulated, and the expression of SLC38A1, SERPINA5, and HOXB2 genes are downregulated." (PMID 38229116, 2024).
skin squamous cell carcinoma (2 papers, 2018 to 2020). A carcinoma arising from the squamous cells of the epidermis. "For example, in skin squamous cell carcinoma, LGR5 modulates Wnt/β-catenin signaling by interacting with and cointernalizing Wnt receptors and delaying endosome degradation." (PMID 29471794, 2018).
triple-negative breast carcinoma (2 papers, 2018 to 2021). An invasive breast carcinoma which is negative for expression of estrogen receptor (ER), progesterone receptor (PR), and human epidermal growth factor receptor 2 (HER2). "High levels of LGR5 expression were significantly associated with tumor size (p = 0.002), LN metastasis status (p = 0.044), and triple-negative breast cancer (p = 0.029), consistent with our findings from the ONCOMINE database." (PMID 29471794, 2018).
uterine diseases (2 papers, 2019 to 2020). "Conditional loss of EZH2 in the uterus upregulated genes associated with uterine diseases, including keratin 5 (Krt5), keratin 15 (Krt15), the maternally-imprinted gene- H19, leucine-rich repeat-containing G-protein-coupled receptor 5 (Lgr5), and cell division cycle associated 5 (Cdca5)." (PMID 33732505, 2020).
Abdominal obesity (1 paper, 2015). Excessive fat around the stomach and abdomen. "The T2D risk allele of rs7903146 in TCF7L2 specifically contributed to an increased risk for T2D combined with abdominal obesity (P = 3.77 × 10−2) and the T2D risk allele of rs7961581 in TSPAN8/LGR5 was related to an increased risk for T2D with elevated TG level (P = 4.61 × 10−2)." (PMID 26599349, 2015).
acute GVHD (1 paper, 2021). "Given these conflicting reports, and the established primacy of the intestinal turnover in acute GVHD pathogenesis, we aimed to determine the impact of PLX2853 BET inhibition on Lgr5+ intestinal stem cells." (PMID 34722316, 2021).
adenosis (1 paper, 2021). "We investigated LGR5 expression in normal terminal duct lobular units (TDLU) and various benign lesions, including adenosis, intraductal papillomas, fibroadenomas, and phyllodes tumors." (PMID 34493772, 2021).
adenovirus infection (1 paper, 2017). "Single Lgr5-GFP+ cells were sorted from CCL4-treated Lgr5-GFP mice at day 5 after CCL4 treatment and then infected with adenoviral Lgr5 shRNA (Ad-Lgr5 shRNA); both the Lgr5 protein expression and Lgr5 messenger RNA (mRNA) expression were decreased at 72 h after adenovirus infection." (PMID 29079780, 2017).
anonychia congenita (1 paper, 2022). "With this in mind, the two additional variants of the gene LGR5 found in the patient with RPSO4-associated anonychia congenita are certainly very interesting, although a potential pathomechanism remains elusive." (PMID 36421794, 2022). "In addition, the index patient was compound-heterozygous for two variants of the related gene LGR5 (c.1997T>C/p.Val666Ala and c.2125C>G/p.Pro709Ala) which might also play a role in combining anonychia congenita with a mild hair phenotype." (PMID 36421794, 2022).
Anosmia (1 paper, 2022). An inability to perceive odors. "Thus, it facilitates us understanding how Lgr5+ cells guide the OE regeneration, providing new insight into the therapy against anosmia induced by sensory neuron degeneration." (PMID 35966594, 2022).
anxiety disorder (1 paper, 2024). A category of psychiatric disorders which are characterized by anxious feelings or fear often accompanied by physical symptoms associated with anxiety. "For instance, oncogenic signaling pathways such as the PI3K/AKT-Wnt/β-catenin pathway in the liver, and the role of Lgr5, may be significant contributors to the pathogenesis of anxiety disorders." (PMID 39335576, 2024).
brain glioma (1 paper, 2014). A malignant glioma that involves the brain. "The results showed that mRNA and protein expression levels of LGR5 markedly increased with an increase in pathologic grade of the brain gliomas (P<0.05)." (PMID 24172981, 2014).
C. perfringens infection (1 paper, 2023). "The decreased expression of Lgr5 and other related stem cell marker genes in the present study revealed that the coccidia and C. perfringens infection caused the intestinal injury of broilers and therefore adversely affected the development of ISCs." (PMID 38136901, 2023).
cholangiocarcinoma (1 paper, 2019). A carcinoma that arises from the intrahepatic biliary tree (intrahepatic cholangiocarcinoma) or from the junction, or adjacent to the junction, of the right and left hepatic ducts (hilar cholangiocarcinoma). "Here we also found that glucose depletion in cholangiocarcinoma organoids induced an increase in their expression of stem cell markers, including LGR5, CD44, EpCAM, NANOG and OCT4 and more pronounced stem cell phenotypic characteristics such as resistance to gemcitabine." (PMID 31835877, 2019). "Exposure of cholangiocarcinoma organoids to glucose-depleted condition increased the intracellular concentration of H2O2 and the expression of LGR5." (PMID 31835877, 2019). "Flow cytometric analysis also demonstrated that the percentage of LGR5-positive cells was significantly reduced by NAC treatment in CCO1 and CCO2, suggesting that suppression of ROS reduced the number of cholangiocarcinoma organoids with a stem cell phenotype." (PMID 31835877, 2019).